ARG1 (arginase 1)
Diseases named in the same sentence as ARG1 in open-access papers (continued):
Sharing a sentence is not in itself a finding about the gene and the disease.
tumor (continued). "Previously, it has been shown that the increased activity of arginase-1 may stimulate tumor growth by attenuating the cytotoxic effect of NO." (PMID 36142391, 2022). "In addition, we observed decreased ARG1 expression and a reduced suppressive function of tumor-educated myeloid cells following ARG1 vaccination." (PMID 36330525, 2022). "As we demonstrated here, Arg1 is a key effector produced by macrophage to promote tumor growth." (PMID 35778404, 2022). "A nomogram based on tumor size, tumor number, platelet, and plasma ARG1 levels could help predict the possibility of early TACE refractoriness before TACE treatment to achieve an individualized prediction of early TACE refractoriness in different patients." (PMID 36212404, 2022). "However, in multivariate analyses we found that only tumor number, tumor size, and platelet and plasma ARG1 levels were independent predictive factors for early TACE refractoriness." (PMID 36212404, 2022). "Hence, ARG1-based immune vaccines that modulate the tumor microenvironment should increase the effect of CPIs." (PMID 36330525, 2022). "In clinical biopsies, tumor Arg-1 expression is localized to granulocytic myeloid cells." (PMID 36230888, 2022). "Treatment with 5-aza-dC and TSA synergistically decreased the mRNA levels of M2 cytokines (il-10, il-4, and tgfb) and a marker (arg1) in tumor tissues, while increasing those of M1 cytokines (il-12p40 and ifng) in tumor tissues, as compared to either therapy alone and in the saline-treated control." (PMID 36483544, 2022). "In primary tumor sites, suppressive myeloid cells recruited by cancer cells play an important role in inhibiting anti-tumor immune responses using many mechanisms extensively reviewed elsewhere (expression of ARG1, production of NO, ROS, and prostaglandin E2)." (PMID 35309358, 2022). "However, CD206 and ARG1 were dramatically reduced by the anti‐Chi3L1 antibody in lung metastatic tumor tissues." (PMID 34861103, 2022). "Notably, tumor-infiltrating macrophages in tumor-bearing Ern1 (-/-) mice had a marked reduction in spliced Xbp1, Il-23p19, Arg1 and Cd274 gene expression compared to their Ern1 fl/fl counterpart." (PMID 35237269, 2022). "T cell-facilitated elimination of arginase-1-expressing cells could potentially restore L-arginine levels and improve anti-tumor responses." (PMID 36330525, 2022). "Arg1 was highly expressed around tumor tissues, but was hardly observed in healthy liver tissues." (PMID 35251971, 2022). "In addition, macrophages expressing arginase-1(Arg1) promoter coupled with firefly luciferase were engineered for bioluminescence imaging (BLI) of the tumor microenvironment." (PMID 35251971, 2022). "qRT-PCR analysis of bulk tumor RNA indicated that ACT+MS-275 treatment downregulated ARG1, NOS2, and TGFB1 expression, which may prohibit Treg expansion." (PMID 35972798, 2022). "As a result, the M1/M2 macrophage ratio was the highest after D-NPDOX/C-NPNLG&BLZ treatment (group 6), and this result was further confirmed by immunofluorescence staining of iNOS (an M1 macrophage marker) and arginase-1 (Arg-1) (an M2 macrophage marker) in tumor sections." (PMID 35440570, 2022). "Prostaglandin E2 (PGE2) is a critical product of cyclooxygenase 2 (COX-2), which is overexpressed in most human cancers, affects tumor progression and immunosuppression, and stimulates arginase-1 (ARG-1) and nitric oxide synthase (NOS)-2 secretion from MDSCs24." (PMID 35058524, 2022). "This may be achieved by identifying predictive biomarkers such as the kinetics of arginine modifications in the blood or the level of overexpression of Arg1 into the tumor tissue and/or myeloid subpopulations." (PMID 35159363, 2022). "The tumor cells were positive for Hep Par-1, Arginase 1 (ARG1), CD10, Glypican-3 (GPC3), and KRT19." (PMID 35789568, 2022). "Similarly, pleural and tumor MC38-related TAMs were found to express less M2 Arg1 gene upon CSF1R blockade." (PMID 35315360, 2022).
tumor (continued). "In addition, the COX2 inhibitor celecoxib blocks MDSCs suppressive function and delays tumor development by decreasing the expression of ARG1." (PMID 36163047, 2022). "In addition, the levels of tumor markers including alpha-fetoprotein, arginase-1, alpha-L-fucosidase, and ferritin were significantly increased, whereas the hepatic miR-122 level was significantly decreased in induced-HCC rats." (PMID 35081125, 2022). "Therefore, combining luciferase expression with activation of the Arg1 promoter is an ideal tool to dynamic monitoring of tumor development." (PMID 35251971, 2022). "Additionally, DIM treatment showed neglectable influence on the mRNA levels of Arg1 and iNOS in splenic MDSCs from miR-21−/− tumor-bearing mice." (PMID 35773674, 2022). "However, immunosuppressive cells (e.g., myeloid cells) and tumor cells in the TME plunder arginine via increased arginase 1 (Arg 1) to restrict T-cell anti-tumor function and survival." (PMID 36231064, 2022). "Therefore, it has already been suggested to investigate arginase-1 as a potential target in tumor therapy." (PMID 33808435, 2021). "First, coculture with tumor cells inhibited the expression of M1-related genes encoding IL-6, TNF-α, and IL-1β and increased the expression of M2-related genes encoding CD163, Arg1, IL-10, TGF-β, and VEGFA, as well as expression of TNF-α and CD163 at protein level." (PMID 34093857, 2021). "Here, we report a new way by which neutrophils could kill tumor cells, namely by releasing arginase-1, either by exocytosis or following cell demise." (PMID 34131176, 2021). "TAMs can promote the growth and survival of cancer cells and suppress the anti-tumour immune response through expression of arginase 1 (ARG1), inducible nitric oxide synthase (iNOS), IL-10, transforming growth factor β (TGFβ), and indoleamine 2,3 dioxygenase (IDO)." (PMID 34885021, 2021). "The ARG1 pathway potentiates proliferation and tissue repair and supports the tumor growth." (PMID 33807310, 2021). "Additionally, exocytosis of neutrophil-released ARG1 mediated by IL-8 leads to the depletion of arginine in the tumor microenvironment, thus hampering proliferation of T cells, and NO generated by NOS2 induces the suppression of CD8+ T cells." (PMID 33413697, 2021). "A potential mechanism has been proposed for ARG1 tumor-promoting functions." (PMID 34476174, 2021). "ARG1 expression was described as a factor promoting tumor growth." (PMID 33807310, 2021). "Collectively, ARG1+ EVS is a novel mechanism of tumor-induced systemic T cell dysfunction." (PMID 34743730, 2021). "The high expression of Arg-1 could consume l-arginine in the tumor microenvironment, seriously inhibited the function of T cells and promoted the occurrence of tumor escape." (PMID 34715880, 2021). "Moreover, in transgenic mice overexpressing Arg1 with breast cancer, the increased number of Tregs infiltrated into the tumor was correlated with enhanced tumor development." (PMID 34885023, 2021). "Tumor M2 macrophages produce more polyamines and consume arginine by increasing ARG1 expression." (PMID 34393804, 2021). "Moreover, the expressions of Arg1 and iNOS in tumor tissue-derived MDSCs were higher than that in splenic MDSCs." (PMID 33717204, 2021). "The authors identified that lactic acid secreted by tumour cells skews macrophages towards Arg1 and Vegfa expression via increased HIF‐1α stabilization, a signalling pathway believed to be only involved in M1 macrophage polarization and that is generally known to be activated via hypoxia." (PMID 33460504, 2021). "Accumulation of immature dendritic cells could contribute to the suppression of dendritic cells and T cells by activation of indoleamine 2,3-dioxygenase and arginase 1 by tumor-derived growth factors." (PMID 35008550, 2021). "For example, ARG1, which may be produced by tumor-infiltrating myeloid cells such as myeloid-derived suppressor cells and macrophages, is a potent inhibitor of T cell responses." (PMID 34625113, 2021).
tumor (continued). "Tumor-induced MDSC inhibit T cell proliferation by causing L-arginine depletion through arginase-1 activity, and in the current study, we did find that AEA induced increased expression of arginase-1." (PMID 33995054, 2021). "Arginase-1 and iNOS activity promote tumor growth that escapes from immune surveillance through the depletion of L-arginine; thus, we analyzed the levels of iNOS and Arginase-1 (Arg-1) expression in the intestine as a result of the activation of MDSCs in a pathological context." (PMID 34299314, 2021). "Specifically, TAMs, myeloid-derived suppressor cells and dendritic cells have been shown to play a crucial role in tumor immune evasion by secreting IL-10, IL-12 and arginase-1, leading to suppression of CD8+ T-cell activity and reduced activity of effector T cells." (PMID 34717714, 2021). "In addition, tumor progression can be achieved by attenuating the immune system, specifically T lymphocyte anti-tumor response, through a high expression of arginase 1 (ARG1) and inducible nitric oxide synthase (iNOS)." (PMID 35008790, 2021). "Other studies have shown that l-ornithine produced by Arg-1 could be further metabolized into polyamines, which were important components in cell differentiation and proliferation as well as promoting tumor growth." (PMID 34715880, 2021). "One study showed that an ARG1 small peptide inhibitor combined with anti-PD-L1 slowed tumor growth." (PMID 34025641, 2021). "Reduced Arg-1 expression in PMN-MDSCs from tumor tissue in vivo, and reduced M-CSFR expression on human cord blood-derived MDSCs in vitro suggest that icaritin may exert its anti-tumor activity via impairing the MDSCs through multiple mechanisms of action." (PMID 33717093, 2021). "Neutrophils are efficient producers of ROS and Arginase 1 (ARG1), which can promote tumor growth." (PMID 34948368, 2021). "Tumor-derived lactate induces the polarization of TAMs towards an anti-inflammatory, proangiogenic phenotype with the expression of arginase 1 (Arg1) and VEGF via the stabilization of HIF-1α and a reduction in the level of the cofactor NAD+, which inhibits pADP-R synthesis." (PMID 34177945, 2021). "Additionally, we assessed Arg1 levels by flow cytometry in CD11b+ cells isolated from tumor-bearing hemispheres at day 21 post-implantation." (PMID 34504786, 2021). "Furthermore, it has been shown that glial cells in the tumor microenvironment stimulate tumor proliferation by expressing arginase-1 (ARG-1)." (PMID 34948010, 2021). "ARG1+ EVs can be phagocytosed by DCs or directly inhibit the proliferation of T cells and inhibit the proliferation of antigen-specific T cells to accelerate tumor progression." (PMID 34743730, 2021). "The anti-tumoral effect was correlated with the generation of CD4+, CD8+ T cells, and CD44+ CD62L- CCR7low CD127low T-effector memory cells, and the reduction of CD4+ CD25+FoxP3+ Tregs, Arg1+ CD11b+ Gr1+, and Arg1+ and CD11b+ Ly6+ myeloid-derived suppressor cell populations within the tumor." (PMID 34957134, 2021). "Thus, the abolishment of ARG-1 expression in TAMs was accompanied by subsequent deceleration of the M2 response and inhibition of polyamine synthesis, required for tumor cell proliferation, angiogenesis, cell invasion and metastasis." (PMID 34764332, 2021). "Moreover, in breast cancer, the tumor cells-derived GM-CSF was shown to induce the ARG1 expression in the myeloid cells through STAT3 (signal transducer and activator of transcription) and p38 MAPK (mitogen-activated protein kinases) signaling pathway." (PMID 35008790, 2021). "Arg1 is a predominant isoform expressed in myeloid cells in the brain of tumor-bearing mice." (PMID 34504786, 2021). "MDSCs, characterized as granulocytic/polymorphonuclear (G/PMN-MDSCs) or monocytic (M-MDSCs) based on their cell lineage of origin, further suppress the anti-tumor immune response through multiple mechanisms including the production of arginase-1, reactive oxygen species, TGF-β, and IL-10." (PMID 34831452, 2021).
tumor (continued). "Tumor exosomes and arginine restriction might also induce ARG1 expression on DCs, further enhancing immunosuppression." (PMID 34078376, 2021). "This dissimilarity reinforces phenotype differences between TAMs and M2-polarized macrophages since, in ischemic tumor domains, TAMs may coexpress ARG1 and iNOS/NOS2, representing an intermediary M1/M2 stage." (PMID 34476174, 2021). "Although TAMs seem to have a low NO production capacity, as is observed in murine mammary and human ovarian tumors, consistent with M2-like and protumor characteristics, simultaneous ARG1 and inducible nitric oxide synthase (iNOS) pathways have been observed in tumor-licensed TAMs." (PMID 34476174, 2021). "Here, reduced expression of ALDH8A1, ALDOB and ARG1 were also shown in tumor tissues." (PMID 35036167, 2021). "The production of inducible nitric oxide synthase (iNOS) and NO are vital factors influencing M1 macrophages bactericidal and tumor-killing activity, while the Arg1 expressed by M2 macrophages is mainly involved in cell proliferation, tumor promotion, and tissue remodeling." (PMID 34635652, 2021). "In addition to its suppressive effect on NO, arginase 1 has been shown to inhibit T lymphocyte receptor (TCR) expression in the tumor microenvironment and thus obstruct specific antigen-dependent responses." (PMID 33126765, 2020). "This is especially apparent in the tumor microenvironment where DCs can be educated toward a protumoral tolerogenic phenotype, characterized by low costimulatory molecule expression, poor antigen presentation, and high expression of Arg1 and IDO." (PMID 32121028, 2020). "Recent study showed that the MEK inhibitors selumetinib could be a complement for anti-CTLA-4 therapy to negate the upregulation of COX-2 and ARG1 in the tumor after the neutralization of CTLA-4." (PMID 32508809, 2020). "However, only a few CD33-CD11b+MDSCs in tumor tissues expressed ARG1 (0.63 ± 0.29% vs 0.17 ± 0.12%) (p > 0.05)." (PMID 32415175, 2020). "Accordingly, myeloid-specific deletion of Hif1a or Arg1 suppresses tumor growth in mice." (PMID 32396064, 2020). "One study suggested that circSLC8A1, derived from the SLC8A1 gene, could act as a sponge of miR-494, which is crucial for migration of MDSCs into tumor site and regulation of the production of ARG1 and iNOS, thus enhancing the tumor immune response." (PMID 33613544, 2020). "Consistently, functional assessment of tumor-infiltrating CHOP−/− MDSCs reveals reduced suppression of T cells, which is associated with decreased ARG1, superoxide, and PNT; furthermore, these CHOP−/− MDSCs acquire a DC-like phenotype and are able to stimulate immune response." (PMID 32793192, 2020). "The promotion of tumor growth was in part mediated by arginase-1 carried by TAM-derived exosomes." (PMID 32498400, 2020). "However, in tumor environment, MDSCs not only have characteristics of M2 macrophages (such as the expression of arginase-1 and NOS2), but also play a role as the progenitor cells of tumor associated macrophages." (PMID 33154947, 2020). "The pro-tumor role of ARG1 was partially confirmed by clinical evidences." (PMID 32133298, 2020). "Neutrophils are recognized as not only important contributors to tumor progression, metastasis and production of proangiogenic factors, but also inhibitors of activity of T cells and natural killer cells through production of arginase-1 and hydrogen peroxide." (PMID 32192443, 2020). "Arginase 1 is a typical marker for M2‐like macrophages that could be induced by tumor lysates and lactic acid." (PMID 32976623, 2020). "In addition, our investigation showed that tumor-infiltrating MDSCs from 6 GAC patients consisted of >35% ARG1-expressing naïve MDSCs (HLA-DR−CD33−CD11b−CD14−CD15−MDSCs), >15% early-stage MDSCs and >40% monocytic MDSCs (HLA-DR−CD14+MDSCs)." (PMID 32415175, 2020).
tumor (continued). "Indeed, suppression of ARG1 activity has immune-mediated anti-tumor effects that inhibit Treg cell proliferation and promote tumor antigen-specific T-cell tolerance." (PMID 33552055, 2020). "Indeed, high expression of arginase-1 (Arg-1) in M2 macrophages leads to the depletion of L-arginine in the tumor microenvironment that is required for T cell fitness and antitumor activity." (PMID 32580431, 2020). "PDAC is a powerful inducer of Arg1 in macrophages, likely from tumor‐derived lactate." (PMID 32039522, 2020). "However, a significantly decreased number of tumor-infiltrating macrophages positive for Arg-1 was observed in IKFM mice." (PMID 33028251, 2020). "Arginase 1 (Arg1) can also impair T cell functions in tumor-bearing mice by depleting L-arginine." (PMID 32422991, 2020). "In a hypoxic TME, tumor-induced macrophage polarization (from M1 to M2) occurs via increased nitric oxide (NO) and decreased arginine in hypoxia, as reflected by transcript levels of arginase 1 (ARG1) and nitric oxide synthase 2 (NOS2) in PDAC models." (PMID 32664564, 2020). "Myeloid-derived suppressor cells (MDSCs) and activated tumor-associated macrophages express ARG1, which consumes arginine to form a microenvironment that is not conducive to T cells, resulting in tumor immunosuppression." (PMID 33511116, 2020). "M1 macrophages characterized by the expression of the inducible type of nitric oxide synthase (iNOS) are proinflammatory, whereas M2 macrophages express high level of anti-inflammatory cytokines (e.g., IL10) and a potent arginase-1 (Arg1) activity to favor tumor cell growth." (PMID 32503591, 2020). "Moreover, the levels of IL-10 and ARG-1 mRNA in tumor tissue as markers for M2 protumor macrophages were assessed by RT-qPCR." (PMID 32340166, 2020). "Although our study highlights that phenotypic characteristics and the quantity of MDSCs, and the levels of ARG1, differ when compared between circulating and tumor-infiltrating MDSCs, our study was limited because there was not a large number of specimens and myeloid cell surface markers." (PMID 32415175, 2020). "In addition, Arg1 supports tumor cell proliferation by producing ornithine and polyamines, whereas iNOS promotes T cell death through NO generation and consequent tyrosine nitration and S-cysteine nitrosation of various proteins." (PMID 31130949, 2019). "In tumor-infiltrating myeloid cells, L-Arg is metabolized by ARG1, ARG2, and iNOS." (PMID 31333642, 2019). "All tumor specimens showed predominantly cytoplasmic staining for ARG1 of variable intensity." (PMID 31278254, 2019). "In addition, Arg-1 was expressed at a much higher level after tumour-bearing macrophage co-cultured with cryo-thermal-activated eosinophils as compared to tumour-bearing macrophage co-cultured with tumour-bearing eosinophils." (PMID 31519961, 2019). "However, the tumor-promoting role of arginase 1 remains controversial as L-arginine also favors tumor cell proliferation and survival." (PMID 31616408, 2019). "Macrophage could induce anti-tumour activity through the depletion of L-arginine by Arg-1 within the tumour microenvironment." (PMID 31519961, 2019). "Since human OvCa cells express ARG1, we questioned whether ARG1 is involved in the regulation of tumor progression." (PMID 31278254, 2019). "Interestingly, iNOS+ M1-like macrophages significantly increased in the tumor stroma of PKF2h mice, whereas arginase-1+ M2-like macrophages tended to decrease." (PMID 30659170, 2019).